CXCR3 (C-X-C motif chemokine receptor 3)
Diseases named in the same sentence as CXCR3 in open-access papers (continued):
Sharing a sentence is not in itself a finding about the gene and the disease.
tumor (continued). "Notably, chemokine receptors, including C-C chemokine receptor type 2, 4, 5, 6, 8, 10 (CCR2, CCR4, CCR5, CCR6, CCR8, CCR10), and C-X-C chemokine receptor type 3, 4 (CXCR3, CXCR4) have been identified as significant factors in the recruitment of Treg cells to the tumor site." (PMID 39000453, 2024). "A subsequent anti-PD-1 treatment did not lead to tumor reduction in CXCR3 knockout mice." (PMID 38928238, 2024). "Importantly, this resulted in reversal of tumour growth restriction compared to infected animals without CXCR3 blockade." (PMID 38271469, 2024). "Notably, the fraction of detected aberrant inflammatory CD8 + T cells positively correlated with the number of MUM1 + plasma cells, suggesting a tumor-load dependent accumulation of aberrant inflammatory CD8 + T cells in the bone marrow at ID, with LAT1 and CXCR3 serving as accurate biomarkers." (PMID 39613747, 2024). "Interestingly, the expression of CXCR3 in tumor mice that did not respond to ICB therapy was significantly reduced." (PMID 39372416, 2024). "Genetic reprogramming CAR T cells to express a CCR that increases tumor infiltration is one strategy that has been considered to enhance CAR homing, as other CCRs expressed by CAR T cells (e.g., CXCR3 or CCR5) do not presently complement the chemokine generated in the tumor." (PMID 39127974, 2024). "On the other hand, as an inverse effect, efficient extravasation of macromolecules such as full-size antibodies into the tumor tissue is limited, and thus, [64Cu]Cu-NOTA-α-CXCR3 may be unable to reach the T cells residing in the TME within the observed time window." (PMID 39196448, 2024). "Altogether, putatively tumor-reactive DP CD8+ T cells expressed higher levels of coinhibitory markers, had a higher proliferative capacity, and acquired a unique chemokine receptor expression profile by the upregulation of CCR5 and CXCR6 and downregulation of CXCR3 and CXCR4." (PMID 38335302, 2024). "Thus, this suggested that, while the high, non-specific secretion of chemokines is associated with poor cytotoxic T-cell infiltration, the specific, localized secretion of CXCR3 and CCR5 ligand chemokines near tumor cells correlates with increased CD8+ T-cell infiltration." (PMID 38339310, 2024). "This confirmed that anti-tumor effects were dependent on CXCR3 expression by T cells and not CCR5." (PMID 38339310, 2024). "Furthermore, “helped” cDC1 upregulate CXCL9/10/11 that may promote attraction of CXCR3+ effector T-cells into the TME, as shown for tumor-infiltrating cDC149,50." (PMID 36639382, 2023). "To further understand the molecular mechanism by which the FGL2-blocking scFv induces CD69+CD8+ TM cell generation, we analyzed CyTOF data for chemokine receptors (i.e., CCR2, CXCR3, CXCR2, and CX3CR1) that may affect T cell infiltration and recruitment to tumor sites." (PMID 36759517, 2023). "The strong increase in circulating stem-like tumor-specific T cells expressing CXCR3 may therefore explain the improved abscopal effect observed here against an established non-irradiated tumor under triple vs. dual therapies." (PMID 37045833, 2023). "Tumours from patients with durable responses are enriched for PDL1+ CXCL10+ macrophages and, based on cell–cell interaction analysis, express high levels of CXCL9/10/11 and are predicted to attract peripheral CXCR3+ CD8+ effector-memory T cells (CD8 TEM) into the tumour." (PMID 38030622, 2023). "While CXCR3 on CD8+ T cells is important for recruitment to virus-infected sites, CCR5 expression on CD8+ T cells is required for the localization of CD8+ T cells at the infected site, suggesting that other chemokines or chemokine receptors contribute to this T cell localization at the tumor site." (PMID 36989357, 2023).
tumor (continued). "According to the interesting work by Liu WS and colleagues, strategy which systematically establishes a score utilizing CXCR3 and its ligands abundances in TME to predict tumor metastasis during NK cell-based ACT and radiotherapy combined therapy may be beneficial and promising." (PMID 38264648, 2023). "Therefore, the promotion or inhibition effect of CXCL10 on tumor immunity may depend on the balance between CXCR3+CD8+ cells and CXCR3+ Tregs." (PMID 36782176, 2023). "In general, CXCR3 is highly expressed on the surface of NK cells, and it drives NK cell-specific chemotaxis toward the CXCR3 ligands CXCL9, CXCL10 and CXCL11, which are secreted by tumor cells into TME and usually expressed at relative low levels in homeostatic condition." (PMID 38264648, 2023). "This may be because CXCR3 activation of the PLC-β/Ca2+ signaling pathway reduces the inward flow of intracellular calcium ions, decreases the adhesion of cells to the substrate through the activation of μ-calpain, and contributes to tumor cell migration." (PMID 36479091, 2022). "Furthermore, inhibition of LINC00152 may increase the number of tumor-infiltrating CD8+ T cells and promote the expression of CXCL9, CXCL10, and C-X-C Motif chemokine receptor 3 (CXCR3) in xenograft tumors, thereby achieving the goal of tumor suppression." (PMID 35402261, 2022). "Of mechanistical relevance, advanced-stage CRC patients could also be characterized by the significantly decreased expression of the chemokine receptor CXCR3 on the surfaces of circulating CD8+ T cells, while the CXCR3 ligand CXCL10 turned out to be upregulated in the tumor tissue." (PMID 36428508, 2022). "Importantly, when the tumour-initiating cells were treated with gemcitabine and, at the same time, the CXCL10-CXCR3 axis was disrupted by the treatment with nanovesicles that contained CXCR3 antagonist, the treatment delayed tumour regrowth." (PMID 35954425, 2022). "In keeping with this, recent studies in subcutaneous mouse tumour models have shown that CXCR3 is not required for tumour infiltration but is important for positioning T cells to receive anti-tumour activation signals from intratumoral DCs when paired with anti-PD-1 therapy." (PMID 35464424, 2022). "Its negative role can be attributed to STAT3 inhibition of CXCR3-driven tumor trafficking." (PMID 35270020, 2022). "To summarize, our results suggest that certain CAF-derived soluble factors downregulated the expression of CXCR3 on CD4+ and CD8+ T cells and CCR5 on CD8+ T cells and upregulated the expression of CXCR4 on CD4+ and CD8+ T cells, which affect their migratory capacity towards tumor cells." (PMID 35954489, 2022). "However, the mechanism of action for how the CXCR3 pathway impacts anti-tumor immunity has not yet been determined." (PMID 35562800, 2022). "Then, we focused on the tumor cell and lymphocyte interactions mediated by chemokines and demonstrated that mTEC-like and mcTEC-like tumor cells in TETs could induce DP cell migration for positive selection through CCL25:CCR9 and CXCL12:CXCR3 interactions." (PMID 36115836, 2022). "We also showed that CAF-derived soluble factors downregulated the expression of CXCR3 on CD4+ and CD8+ T cells and CCR5 on CD8+ T cells and upregulated the expression of CXCR4 on CD4+ and CD8+ T cells, potentially affecting their migratory capacity towards tumor cells." (PMID 35954489, 2022). "Furthermore, the role of CAFs in CXCR3-mediated modulation of tumor immune cells is as yet not known." (PMID 34203869, 2021). "Thus, the CXCR3 axis regulates the recruitment and activation of NK cells, CD8 T cells, and CD4 Th1 cells, and multiple lines of evidence support the activity of this axis in tumor control." (PMID 34067089, 2021).
tumor (continued). "In conclusion, our studies investigated the role of IFN-γ in the control of established SCC tumours in a UV-induced SCC rejection model and showed that IFN-γ plays a critical role in the induction of chemokines that permit the infiltration into- and destruction of- SCC by CXCR3+ CD8 T cells." (PMID 33925140, 2021). "Similarly, in a model of adoptive T cell transfer, CXCR3 expression was necessary for tumor control, but not for cytotoxic T cell function." (PMID 32273499, 2020). "Moreover, flow cytometric analyses confirmed the increased levels of CXCR3+CD8+ T cells after combined regorafenib/anti-PD1 therapy in the tumor tissue but not in the spleen." (PMID 33234602, 2020). "It was postulated that patients lacking biologic mediators, like CXCR-3 related to lymphatic spread, may have tumor with less aggressive traits and carry a favorable prognosis." (PMID 33329946, 2020). "Furthermore, high expression of CXCR3 protein was closely correlated with the increased recruitment of CD4+, CD8+ tumor infiltrating lymphocytes (TILs), and dendritic cells, which may partly explain the favorable prognosis in GC." (PMID 31240220, 2019). "Others have also shown CXCR3 to be non-redundant to T-cell recruitment into the tumor." (PMID 31379850, 2019). "In tumor lesions, CXCR3 expression might be sustained by the presence of pro-inflammatory molecules such as IFNγ that has been shown to sustain Tbx21 expression and subsequently TBET to positively regulate CXCR3 expression at the surface of T cells." (PMID 30420855, 2018). "The declining expression of CXCR3A and CXCR3B together with the low levels of CXCR3 ligands detected in MPTC, suggest that in cancer thyrocytes, CXCR3 signaling may not be involved in tumor dissemination and LNM." (PMID 29416784, 2018). "As CXCR3-mediated recruitment appears crucial for T cell entry into tumors and as Treg reduce CXCL9 and CXCL10 expression in tumors, we were eager to determine the source of CXCL10 in tumor tissue, and determine if CXCL10-producing cells were indeed affected by Treg depletion." (PMID 29671006, 2018). "Our study investigates CXCR3 kinetics in tumor cells and not immune cells." (PMID 29146996, 2017). "According to the strong signal for CXCL10 in transformed epithelial cells, it is possible that attraction of CXCR3+ Th1 cells by transformed epithelial cells may enhance IFN-dependent production of COX2 in tumor areas, enhancing local tumor angiogenesis and immunosuppression." (PMID 28567040, 2017). "Taken together, our results are in favor of a role of CXCR3 and LRP1 in tumor cell invasion and infiltration, where LRP1 is downregulated at the invasive areas to allow accumulation of CXCR3 at the cell membrane leading to a sustained CXCR3 activation and increased tumor cell invasion." (PMID 29146996, 2017). "However, in both peritoneal and omental metastases we almost exclusively found CXCR3-overexpressing cancer cell populations regardless of its expression in the corresponding primary tumor (immunohistochemistry score 2+ or 3+)." (PMID 28504691, 2017). "However, neither the specific roles of the CXCR3 isoforms nor the mechanisms of activation and the regional variations of expression within the tumor have been investigated in these studies." (PMID 29146996, 2017). "Not surprisingly, MC38-luc tumor-bearing CXCR3−/− mice lived shorter than those of wild type mice." (PMID 26956047, 2016). "To confirm that CXCR3 expression does not promote T-cell migration to the MCA-induced tumours, we performed adoptive transfer experiments where spleen cells purified from WT and CXCR3−/− mice were labelled with the fluorescent dyes, PKH26 and Cellvue Claret, respectively." (PMID 25495686, 2015).
tumor (continued). "Furthermore, dasatinib in combination with the DC-vaccine upregulated Type-1 T cell-recruiting CXCR3-ligand chemokines in the tumor stroma, which correlated with the activation and recruitment of Type-1, vaccine-induced CXCR3+CD8+ TILs and CD11c+ DC into the tumor." (PMID 25709607, 2015). "The tumor cells derived from the tumor tissues had significantly higher expression of CXCR3 compared the tumor cells in culture when the same non-enzymatic dissociation procedure was applied to the preparation of the single cell suspension for flow cytometry analysis." (PMID 26485767, 2015). "In addition, we compared the staining of CXCR3 and CD45 (pan-leukocyte marker), CK8 (pancreatic epithelial marker) and α-smooth muscle actin (α-SMA, marker of activated fibroblasts/PSCs) between the tumor and the adjacent normal tissue for each patient." (PMID 25415223, 2014). "However, the extent of tumour development was never significantly enhanced in the AMG487-treated mice compared with the corresponding control group, indicating that the CXCR3 antagonism did not affect the local tumour growth." (PMID 19436305, 2009). "CXCR3 expression on NK cells plays a dual role in the TME: it can enhance NK cell recruitment and promote a highly cytotoxic phenotype, but persistent CXCR3 signalling in an immunosuppressive TME may lead to NK cell dysfunction and impaired tumour clearance, contributing to immune evasion." (PMID 40361472, 2025). "Notably, RT plus Y332D markedly enhanced the infiltration of CXCR3+ T, CXCR3+ CD8+ T, CXCR3+ CD4+ T, and CXCR3+ NK cells versus either monotherapies or vehicle, potentially due to the recruitment of CXCR3‐positive lymphocytes into the tumor by CXCL10 secreted by tumor cells, which is promoted by RT." (PMID 40470716, 2025). "We found that expression of CXCR3 (C-X-C motif chemokine receptor 3), a homing receptor that is highly expressed on activated T cells to enable trafficking to inflammatory sites, remained high in our model irrespective of the presence or absence of tumor cells or autologous MDMs." (PMID 39414902, 2024). "Moreover, CXCR3, which is the corresponding receptor of Cxcl9 and Cxcl10, is expressed by stem-like CD8+ Tpex cells and functions in CD8+ T-cell migration and positioning within tumors, as reported by prior studies, was significantly upregulated in CD8+ T cells after LDRT treatment of tumor." (PMID 38001101, 2023). "Moreover, using multiple HCC preclinical models and an ex vivo tumor fragment platform, we dissect the mechanisms by which LDRT sensitizes DPVB by enlarging intratumoral stem-like CD8+ Tpex, which are recruited from the draining lymph nodes (dLNs) into the tumor through the CXCL10/CXCR3 axis." (PMID 38001101, 2023). "When examining the factors that could contribute to CD8+ Teff tumor recruitment, we found that CD8+ Teffs expressed the chemokine receptors CXCR3 and CXCR4, while the TME produced abundant CXCL9 and CXCL12, which are the key chemokines known to bind CXCR3 and CXCR4, respectively." (PMID 35552271, 2022). "Furthermore, CCR5-CCL4/CCL5 and CXCR3- CXCL9/CXCL10/CXCL11/CXCL13 axis were significantly correlated with CD 4 T and CD 8 T cells, indicating that these interactions may be essential for the recruitment of the T lymphocytes into tumor." (PMID 35530341, 2022). "Moreover, tumor tissues with a high T cell ratio within and close to the tumor nests in relation to the total stroma produced higher levels of CXCL9, CXCL10 and CXCL11, signifying the importance of the CXCR3-axis in T cell localization within the tumor microenvironment." (PMID 35954489, 2022). "However, blockading CXCR3 failed to affect tumor growth, suggesting that tissue-resident NK cells may compensate for decreased migration of NK cells from the circulation." (PMID 35768424, 2022).
tumor (continued). "Consistent expression of CXCR3 on both subsets and selective late expression of CXCR6 on resident memory cells suggest that while CXCR3 may direct default peripheral migration of both memory subsets to the tumor, CXCR6 selectively promotes tissue residency of memory cells." (PMID 34607898, 2021). "It has been demonstrated that normal gut microbiota might enhance the anti-tumor activity of ICIs by promoting the secretion of IL-12 by local dendritic cells and by changing the local repertoires of Th1 cells to express the intestinal chemokine receptors CCR9 and CXCR3." (PMID 33578709, 2021). "However, studies revealed that anti-CXCR3 did not reduce the tumor size of the established tumor." (PMID 34359780, 2021). "Therefore, the promotion of STAT‐5 signalling might not only promote CXCR3 expression and the homing of CAR T cells to CXCL9/10‐expressing tumours, but also contribute to the acquisition of CTL activity probably through the induction of T‐bet and thereby CAR T‐cell function." (PMID 31803974, 2020). "Also notable is a minimal change in expression of the chemokine CXCR3 but a significant increase in the expression of its ligands, CXCL10 and CXCL11, which are important in activating other signaling molecules that recruit immune cells for the general enhancement of anti-tumor pathways." (PMID 31795829, 2019). "Intriguingly, as the therapeutic effect of CXCR3 inhibition was compromised in mice depleted of NK cells or with mutations in IFN-γ, it has been suggested that the role of CXCR3 is not simply to mediate tumor cell trafficking but also to support antitumor immunity." (PMID 30591657, 2018). "In addition, our work demonstrates that CXCR3 inhibition may provide double benefits for inhibiting tumor and improving host immunity, unlike most agents that are effective in targeting tumor cells but are toxic to host cells." (PMID 26485767, 2015). "CXCR3, which is present on activated MO/MAs and on activated T cells, binds several rIFN-γ1b- induceable chemokines, including CXCL9/Mig, CXCL10/IP-10, and CXCL11/I-TAC These chemokines might facilitate recruitment of activated leukocyte subsets to the tumor site." (PMID 16603073, 2006). "Last, but not least, there is growing evidence that CXCL9/CXCL10/CXCR3 and CXCL16/CXCR6 are involved in tumor pathogenesis, so they probably represent pleiotropic chemokines at the crossroads of immunity and carcinogenesis." (PMID 41373861, 2025). "Consistent with this, the primary ligands for CXCR3, CCR5 and CXCR6 correlated with T-cell- and macrophage-specific genes, but not with tumor cells, B cells or fibroblasts." (PMID 41415437, 2025). "Neurons in the TME release CXCL10, which interacts with CXCR3 on Nonneurogenic tumor cells, activating downstream pathways (Akt, MEK, RAC) that facilitate tumor infiltration into peripheral nervous tissues." (PMID 39429695, 2024). "CXCR3 has low expression in non-tumor tissues, and low expression of CXCR3B can inhibit tumor cell spreading, so high CXCR3B expression suggests good prognosis." (PMID 36479091, 2022). "In our mouse tumor models, functional CXCL11, the third ligand for CXCR3, is lacking in C57BL/6 mice." (PMID 35013216, 2022). "Notably, the co-incubation with AML exosomes reduced CXCR3 expression on NK-92 cells surface, suggesting that down-regulation of CXCR3 levels by AML exosomes might be ligand-mediated and responsible for the decreased migration of NK-92 cells into the tumor site." (PMID 35031075, 2022). "Based on this mechanism, it is believed that IL-18 and IP-10/CXCL10 do not exert tumor-suppressive effects, but rather, promote IFN-γ secretion and chemoattraction of CXCR3+ cells into the NPC TME." (PMID 33718235, 2021). "This, alongside a significant increase in CXCR3 expression on the CD8+ T cells within the draining lymph node, suggest that the T cells were primed for migration, potentially to the tumor." (PMID 34336705, 2021).